APOE (apolipoprotein E)
Diseases named in the same sentence as APOE in open-access papers (continued):
Sharing a sentence is not in itself a finding about the gene and the disease.
ischemic stroke (44 papers, 2001 to 2026). A stroke disorder caused by obstruction of blood flow to the brain, due to thrombotic (local blood clot formation) or embolic (due to a blood clot or other material traveling from another site) event. "Meta-analysis results, total sample and sex-specific, of the association of APOE-rs429358 (chr19:45,411,941, b37) with the ischemic stroke age at onset in discovery (SiGN) and replication (FinnGen and WHI) cohorts." (PMID 39286457, 2024). "We found that APOE-rs429358, encoding the ApoE-Є4 haplotype, is associated with an earlier age at ischemic stroke in women." (PMID 39286457, 2024). "Although association between APOE ε4 genotype and unfavorable outcome have been reported in ischemic stroke, there are relatively limited data with adjustment for inflammation level." (PMID 36640294, 2023). "Rising studies indicate that the apolipoprotein E (APOE) gene is related to the susceptibility of ischemic stroke (IS)." (PMID 35154509, 2022). "Future studies should elucidate the biological mechanisms behind the association between APOE ε4 allele count and younger age at ischemic stroke onset." (PMID 31619479, 2019). "We derived the 3 common APOE alleles and investigated the interplay between APOE, age at ischemic stroke onset, severity, sex, and outcome within a large international collaboration, the Genetics of Ischaemic Stroke Functional Outcome (GISCOME) network." (PMID 31619479, 2019). "This is the largest meta-analysis with combined information on common APOE alleles, age at ischemic stroke onset, severity, and outcome to our knowledge." (PMID 31619479, 2019). "Pedro-Botet et al13) first reported that the variant ε4 of apoE was positively associated with ischemic stroke in men." (PMID 11434425, 2001). "Additionally, APOE ε4 carriers have been reported to exhibit higher carotid intima-media thickness and a greater risk of ischemic stroke, emphasizing its impact on cerebrovascular health." (PMID 40671162, 2025). "Lower ApoE levels (aOR 0.13, 95% CI 0.03–0.68, p = 0.015), abnormal cIMT ≥0.70 mm (aOR 2.72, 95% CI 1.08–6.85, p = 0.033), and alcohol use (aOR 1,078, 95% CI 4–267,933, p = 0.013) were independently associated with ischemic stroke in multivariable analysis." (PMID 41541874, 2025). "This APOE variant has previously been associated with increased mortality and ischemic stroke AAO." (PMID 39286457, 2024). "That is why we explored the relationship between APOE gene polymorphisms and ischemic stroke risk." (PMID 35154509, 2022). "Unexpectedly, ischemic stroke in the context of cerebral β-amyloidosis drives the emergence of a neuroprotective microglial phenotype characterized by an ApoE-enriched transcriptional state and enhanced lipid handling." (PMID 42265753, 2026). "This study develops an innovative ApoE‐mimetic peptide‐capped GNPs, which provides a potential strategy for the treatment of ischemic stroke." (PMID 40102637, 2025). "After adjusting for potential confounders using a multivariable conditional logistic regression model, lower ApoE levels, abnormal cIMT ≥0.70 mm, and alcohol use were independent predictors of ischemic stroke." (PMID 41541874, 2025). "There is increasing evidence indicating that apolipoprotein E (ApoE) can be a potential candidate for the treatment of ischemic stroke." (PMID 40102637, 2025). "In this prospective cohort study, we recruited patients aged ≥20 years who had ischemic stroke within the past 7 days and measured their ApoE genotype." (PMID 40349252, 2025). "Utilizing a case-only GWAS design, we identified a significant association between the APOE locus, specifically the rs429358 variant, and AAO of ischemic stroke." (PMID 39286457, 2024). "At the receiver operating characteristic (ROC) analysis, the area under the curve (AUC) of combining NLR and APOE genotype for poor functional outcome after ischemic stroke was 0.673 (0.641-0.704)." (PMID 36640294, 2023).
ischemic stroke (continued). "All these clinical studies support that ApoE is involved in the pathogenesis of ischemic stroke and our study reveals how ApoE mediates the cross-talk between astrocytes and endothelial cells under the condition of ischemic stroke." (PMID 32513932, 2020). "We investigate the neuroprotective and anti‐inflammatory properties of the apolipoprotein E mimetic pentapeptide, CN‐105, in a microglial cell line and murine model of ischemic stroke." (PMID 28382306, 2017). "Our study has demonstrated that CN‐105, an apoE‐mimetic pentapeptide, reduces mortality, infarct volume, microgliosis, and improves long‐term functional outcome in a murine reperfusion model of ischemic stroke." (PMID 28382306, 2017). "Hence, designing short peptides with ApoE neuroprotective effects is a potential strategy for ischemic stroke." (PMID 40102637, 2025). "Indeed, brain injury after ischemic stroke has been shown to be exacerbated in ApoE−/− mice, demonstrating the relevance of using such models." (PMID 35628192, 2022). "However, little is yet known about an epigenetic impact of ABCG1 and APOE on the development of ischemic stroke." (PMID 31823830, 2019). "In conclusion, this study shows that APOE ε4 carriers have a younger age at ischemic stroke onset." (PMID 31619479, 2019). "It has been suggested that another protein involved in neuronal repair, regeneration and survival, apolipoprotein E (ApoE), may differentially affect outcome in hemorrhagic and ischemic stroke." (PMID 25470006, 2014). "ApoE protein is involved in cholesterol transport and some studies suggest ApoE *ε 4 and ApoE *ε 2 alleles are associated with higher risk and lower risk of ischaemic stroke respectively, but this has not been confirmed in all studies." (PMID 17553166, 2007). "Some studies suggest APOE*ε4 and APOE*ε2 alleles are associated with higher risk and lower risk of ischaemic stroke respectively, although this has not been confirmed in all studies." (PMID 16551349, 2006). "The aim of this study was to explore whether DNA methylation loci located in the ATP-binding cassette G1 (ABCG1) and apolipoprotein E (APOE) genes, both involved in the metabolism of lipids in the body, are related to ischemic stroke, using the Fangshan/Family-based Ischemic Stroke Study in China." (PMID 31823830, 2019). "In addition, ApoE is a multifunctional protein that plays a key role in cholesterol metabolism; a higher level of APOA1 is considered to be protective against ischemic stroke, and taurocholic acid can lower postprandial lipemia." (PMID 37009888, 2023). "As with ApoE, this suggests BNDF may differentially affect outcome in hemorrhagic and ischemic stroke." (PMID 25470006, 2014). "The interaction of APOE genotype and NLR on ischemic stroke outcome has not been fully addressed." (PMID 36640294, 2023).
glioblastoma (43 papers, 2014 to 2026). The most malignant astrocytic tumor (WHO grade IV). "Differential RNA‐fragment abundances in glioblastoma aggregates, in which only the APOE allele differs between cell lines, tend to be highly significant (53 of 59 have p < 0.0001) and comprise an interesting set." (PMID 33788386, 2021). "The ε4 allele of apolipoprotein E (ApoE) is a genetic variant critical for neuronal growth and repair and associated with increased susceptibility to cognitive and language dysfunction in such brain tumours as glioblastoma." (PMID 39598176, 2024). "One study found that knocking down APOE in glioblastoma cells altered cytokine secretion (increased IL-6/IL-12/TNF-α and decreased CCL5/TGF-β) and reduced the proportion of M2 macrophages in a co-culture system." (PMID 40745073, 2026). "A recent study implicated TNS3 in microglial gene networks in glioblastoma and AD and reported an inverse correlation between TNS3 and APOE expression levels." (PMID 41404291, 2025). "Recent studies use ApoE‐directed, redox‐responsive virus‐mimicking polymersomes to deliver GrB to glioblastoma cells, enhancing delivery and opening new possibilities for targeted immunotherapy." (PMID 40249282, 2025). "In glioblastoma, the cholesterol transporter apolipoprotein E (ApoE) accumulates around the tumor, leading to cholesterol accumulation in TAMs." (PMID 38302980, 2024). "Liposomal constructs modified with apolipoprotein E and rabies virus glycoprotein were used to encapsulate gold-functionalized SNAs for delivery into glioblastoma cells in vitro and glioblastoma tumors in vivo." (PMID 39457052, 2024). "In this regard, a recent study has shown that APOE can translocate to the nucleus and bind to DNA to function as a transcription factor in human glioblastoma cells." (PMID 38734844, 2024). "The OMIs encapsulated in SNA-gold liposome-ApoE were protected from degradation by serum components, indicating higher payload delivery to glioblastoma even in the presence of high protein and nuclease concentrations found in plasma." (PMID 37860265, 2023). "APOE overexpression has been observed in diverse cancers, including gastric, lung, prostate, thyroid, ovarian, endometrial cancer, and glioblastoma." (PMID 38136890, 2023). "Relative to APOE genotypes, it designated a greater aggregation of mitochondrial and accumulated proteins in T98G cells (glioblastoma) communicating APOE3 vs. APOE4." (PMID 37109499, 2023). "Comparison of APOE genotypes indicated a larger accumulation of mitochondrial and aggregated proteins in glioblastoma T98G cells expressing APOE4 vs APOE3." (PMID 35665766, 2023). "It has previously been shown that curcumin incorporation into stable nanodiscs surrounded by either apolipoprotein ApoA1 or ApoE increases the efficiency of curcumin delivery and apoptosis induction in hepatoma, lymphoma, and glioblastoma cell lines." (PMID 36296810, 2022). "Studies on several tumors, including glioblastoma, EC, lung cancer, and prostate cancer, showed that when APOE is overexpressed, the disease is more aggressive, and the prognosis is poor." (PMID 36551747, 2022). "To ascertain ApoE allelic form and A03 effects on sAPPα in vitro, we used transiently-transfected human glioblastoma cells because they express human APP and enzymes." (PMID 30514854, 2018). "Very interestingly, we found that thecellular uptake of ApoE-rHDL in glioblastoma cells is much higher than that in normalprimary astrocytes." (PMID 28489075, 2017). "At the same time, ApoE peptide-functionalized liposomes enable active targeting of glioblastoma." (PMID 40806525, 2025). "In addition, the study reported that APOE knockdown in glioblastoma cells attenuated tumor migration/invasion while reprogramming cytokine secretion—elevating antitumor cytokines (IL-6/IL-12/TNF-α) and suppressing immunosuppressive CCL5/TGF-β." (PMID 41390817, 2025).
glioblastoma (continued). "In these studies, curcumin nanodiscs with ApoA1 scaffold protein showed increased apoptosis in human hepatoma and lymphoma cell lines over curcumin alone controls, and ApoE curcumin nanodiscs demonstrated increased apoptosis and bioavailability in glioblastoma cells." (PMID 36296810, 2022). "Also, U87 produces low levels of APOE RNA, we have instead used another glioblastoma cell line LN-229 (with higher APOE RNA expression than U87) for this experiment." (PMID 31978088, 2020). "Apolipoprotein E3-reconstituted high-density lipoprotein is used toencapsulate the siRNA-loaded calcium phosphate core and facilitate it to penetratethe blood–brain barrier, thus targeting the glioblastoma cells in amacropinocytosis-dependent manner." (PMID 28489075, 2017). "Researchers have designed acid-sensitive bionic nanocarriers based on ApoE peptide-modified erythrocyte membranes for the delivery of Bcl-2/Bcl-xl and Mcl-1 inhibitors to treat glioblastoma (GBM)." (PMID 40420216, 2025). "In our study, however, we used human glioblastoma astrocytes with identical genetic material to specifically assess potential differences in the ability of CSF lipoproteins to promote cellular cholesterol efflux, thereby minimizing any confounding effects from cellular APOE variations." (PMID 40701521, 2025). "ApoE-Ph nanoagents have a higher PTT efficiency for glioblastoma (GBM) by keeping the balance of radiation-modulated NIR-fluorescence imaging at 1,550 nm and non-radiation NIR-PTT, opening a novel window for boosting theranostics in other cancers." (PMID 36590281, 2022). "ApoE‐functionalized nanosystems, like polymersomes, can navigate the BBB and target glioblastoma, improving therapeutic delivery." (PMID 40249282, 2025). "For example, incorporation of targeting peptides, such as apolipoprotein E (ApoE), which binds low-density lipoprotein receptors (LDLRs) expressed on both BBB endothelial cells and glioblastoma cells, has shown high potential for enhancing brain delivery." (PMID 41302542, 2025). "A biologicallyinspired nanostructure CaP-rHDL, derived from ApoE-rHDL that can sufficiently crossthe BBB, was core-loaded with siRNA with a high efficiency and served as aneffective delivery tool for anti-glioblastoma therapy." (PMID 28489075, 2017). "In addition, the cellular uptake of ApoE-rHDL in glioblastoma cellswas largely inhibited by the inhibitors of macropinocytosis, amiloride andethylisopropylamiloride (EIPA), indicating that macropinocytosis might serve as a uniquemechanism for the glioblastoma-specific accumulation of ApoE-rHDL." (PMID 28489075, 2017). "PEGylated ApoE-functionalized BMCNPs demonstrated significantly extended circulation times in glioblastoma-bearing animals (8.2 h vs. 6.7 h) compared to non-targeted BMCNPs." (PMID 41302542, 2025). "ApoE-Ph NPs were reported with fluorescence imaging ability at 1550 nm and higher efficiency of PTT, which could cross BBB and target glioblastoma benefited from the ApoE structure." (PMID 35781601, 2022). "In our study, however, we used human glioblastoma astrocytes with identical genetic material to specifically assess potential differences in the ability of CSF HDL-like to promote cellular cholesterol efflux, thereby minimizing any confounding effects from cellular APOE variations." (PMID 39764088, 2024). "For example, RGCC, SPP1 (osteopontin), GPNMB, and APOE are highly expressed in hepatocellular carcinoma (HCC), whereas PLVAP (PV1), CD276 (B7-H3), and ESM1 are predominantly expressed in glioblastoma (GBM)." (PMID 41303611, 2025).
glioblastoma (continued). "We report here that Hpt impairs ApoE-mediated cholesterol uptake in human neuroblastoma cell line SH-SY5Y, and limits the toxicity of a massive concentration of cholesterol for these cells, while it does not affect cholesterol efflux from the human glioblastoma-astrocytoma cell line U-87 MG." (PMID 25140128, 2014).
chronic kidney disease (41 papers, 2009 to 2026). Impairment of the renal function secondary to chronic kidney damage persisting for three or more months. "We established a mouse model of chronic kidney disease (CKD) using male ApoE-deficient mice who had undergone a 5/6 nephrectomy (5/6NR) and used this model to assess the effect of AST-120 on physical and biochemical parameters." (PMID 31666542, 2019). "It was speculated that rosuvastatin/sarpogrelate treatment would affect the regulation of cholesterol efflux, in particular of LDL cholesterol, and its complication in ApoE-deficient mice with HD-induced chronic renal failure." (PMID 33029491, 2020). "A similar suggestion was previously made in a model of chronic renal disease using ApoE−/− CatS-deficient or ApoE−/− mice treated with specific CatS inhibitors, where these mice showed a significantly reduced vascular calcification associated with fewer aortic elastin breaks." (PMID 31273243, 2019). "The APOE gene has been reported to be indirectly associated with chronic kidney disease." (PMID 28986523, 2017). "RNA-seq data from aortas of atherosclerotic calcification (ApoE-/- mice) and medial calcification induced by chronic kidney disease (CKD mice) were obtained from the GEO database." (PMID 40810067, 2025). "The silencing of nAChRα1 significantly reduces both calpain-1 and calpain-2 activities and talin (a calpain substrate) degradation in murine renal macrophages isolated from an apolipoprotein E knockout (ApoE-/-) mouse model of chronic kidney disease." (PMID 41294867, 2025). "Fth1 was identified as a differentially expressed gene significantly upregulated in the aorta of both ApoE-/- mice (atherosclerotic calcification model) and chronic kidney disease (CKD) mice (medial calcification model)." (PMID 40810067, 2025). "While GDF15 has tissue-protective properties, as shown in acute kidney injury and chronic kidney disease, it promoted vascular injury and GDF15 deficiency protected against brachiocephalic trunk lumen stenosis after a cholesterol-enriched diet in ApoE−/− mice." (PMID 38732029, 2024). "Conversely, other previous studies have shown that the miR-126 level was increased in the aortas of ApoE KO mice with superimposed chronic kidney disease." (PMID 29642385, 2018). "The APOE-e4–allele is suggested to be protective against AKI, as is the case with chronic kidney disease." (PMID 26627480, 2015). "Thickening of the aortic valve leaflets in apoE-/- mice was induced by producing mild or moderate chronic renal failure resulting from unilateral nephrectomy (1/2 NX, n = 18) or subtotal nephrectomy (5/6 NX, n = 22), respectively." (PMID 19257900, 2009). "Apolipoprotein E polymorphisms (APOE) have been associated with lowered glomerular filtration rate (GFR) and chronic kidney disease (CKD) with e2 allele conferring risk and e4 providing protection." (PMID 19852818, 2009). "By contrast, APOE ε4 is associated with increased risk of CVD and end stage renal disease." (PMID 20074603, 2010). "However, the ARIC study found the strongest associations between apoE type and their endpoint, progression of chronic kidney disease, among the African American subgroup, with a non-significant result for the Caucasians." (PMID 19274077, 2009). "In groups of uraemic ApoE −/− mice exposed to chronic renal failure, non-uraemic ApoE −/− and control C57Bl/6J mice, accumulation of tracer in the aorta was observed at week 12 in the ApoE −/− groups." (PMID 36613797, 2022). "We screened UA-related covariables and found that age (p = 0.027), sex (p < 0.001), APOE gene (p = 0.007) and glomerular filtration rate (GFR) estimated by the Chronic Kidney Disease Epidemiology Collaboration creatinine equation (CKD-EPI eGFRCr) (p = 0.002) were related to sUA." (PMID 35923549, 2022).
chronic kidney disease (continued). "For example, hs-CRP levels were not considerably different between APOE genotype carriers in Moroccan patients with end-stage renal disease (ESRD), and, in our study, some ε4 carriers exhibited high CRP levels." (PMID 27177774, 2016).